CDCA8 (cell division cycle associated 8)
Diseases named in the same sentence as CDCA8 in open-access papers (continued):
Sharing a sentence is not in itself a finding about the gene and the disease.
thyroid cancer (2 papers, 2022 to 2023). "In order to further study the effect of CDCA8 on the growth of thyroid cancer, a mouse xenograft model was established." (PMID 35517403, 2022). "We then used RNA-seq analysis to analyze the gene expression profile of TPC-1 cells transfected with shCtrl or shCDCA8, so as to further explore the downstream mechanism of CDCA8 in regulating thyroid cancer." (PMID 35517403, 2022). "In order to explore the mechanism of CDCA8 regulating thyroid cancer, we constructed the CDCA8 knockdown and CDK1 overexpression TPC-1 cells, and compared with the results of only CDK1 overexpression cell model." (PMID 35517403, 2022). "In terms of thyroid cancer, previous study has initially identified CDCA8 as a key biomarker in anaplastic thyroid cancer." (PMID 35517403, 2022). "Downregulation of CDCA8 in thyroid cancer cells suppressed the cell or tumor growth of thyroid cancer in vitro or in vivo." (PMID 35517403, 2022). "Subsequently, we verified the expression of CDCA8 in 40 tumor samples and their paracarcinoma thyroid tissue, and immunohistochemistry analysis showed that the expression of CDCA8 in thyroid cancer tissues was significantly increased." (PMID 35517403, 2022). "The oncogene-like functions of CDCA8 in thyroid cancer were clarified by its upregulation in thyroid cancer, and knockdown of which suppresses thyroid cancer development in vitro and in vivo." (PMID 35517403, 2022). "Considering the up-regulation of CDCA8 in thyroid carcinoma, we used B-CPAP and TPC-1 cells transfected with shCDCA8 lentiviral vector to detect cell function, and shCtrl transfected cells were used as negative control." (PMID 35517403, 2022). "Moreover, the subsequent mechanism research showed that CDCA8 regulated the expression of CDK1 thus influencing the development of thyroid cancer." (PMID 35517403, 2022). "Therefore, this work displays the promising potential of CDCA8 as a therapeutic target in the future development of molecular targeted drugs for thyroid cancer." (PMID 35517403, 2022). "Further, results of preliminary mechanistic exploration showed that CDK1 may be a potential downstream molecule of CDCA8 in regulating thyroid cancer progression." (PMID 35517403, 2022). "Moreover, CDCA8 depletion also induced cell apoptosis and disturbed cell migration ability of thyroid cancer cells." (PMID 35517403, 2022). "More importantly, all the regulatory effects induced by CDK1 overexpression could be alleviated or even reversed by CDCA8 knockdown, indicating its potential as the target of CDCA8 during regulating thyroid cancer." (PMID 35517403, 2022). "Herein, CDCA8 obviously presented higher expression in thyroid cancer tissues than normal tissues." (PMID 35517403, 2022). "All these results indicated that the development and progression of thyroid cancer could be possibly driven by CDCA8, and knockdown of which may be a promising strategy for the treatment of thyroid cancer." (PMID 35517403, 2022). "However, the exploration on the role of CDCA8 in the development and metastasis of thyroid cancer remains to be insufficient." (PMID 35517403, 2022). "In this study, our results delineated the significant upregulation of CDCA8 in thyroid cancer tissues, which may lead to fast progression thus advanced tumor stage of thyroid cancer patients." (PMID 35517403, 2022). "Moreover, CDK1 was identified as a potential target of CDCA8 for exerting its effects on thyroid cancer." (PMID 35517403, 2022). "Consistently, the upregulation of Fas and FasL in shCDCA8 group of cells was detected, by which may CDCA8 influence the cell apoptosis of thyroid cancer." (PMID 35517403, 2022). "Although this study was limited by several drawbacks such as the insufficient clinical samples and the not fully understanding of mechanism, the outcomes allow us to present the first report of the role played by CDCA8 in the development and progression of thyroid cancer." (PMID 35517403, 2022).
thyroid cancer (continued). "Through high-content screening of the inhibitory effects on cell proliferation by gene knockdown, CDCA8 was identified as the most promising candidate among the differentially expressed genes obtained by RNA-seq between thyroid cancer and corresponding normal tissues." (PMID 35517403, 2022). "In view of the enrichment of DEGs in cyclins and cell cycle regulatory signaling pathways, we speculated that CDCA8 may promote the development of thyroid cancer by upregulating CDK1." (PMID 35517403, 2022). "In addition, this work further describes the investigation of downstream mechanism of CDCA8 regulating the progression of thyroid cancer." (PMID 35517403, 2022). "Additionally, CDK1 was further identified as a potential target of CDCA8 in thyroid cancer." (PMID 35517403, 2022). "The in vitro fundamental assessment of CDCA8 manifested that CDCA8 may act as a tumor promotor in thyroid cancer through regulating cell proliferation, formation of colonies, cell apoptosis and cell migration, the validation of which was also confirmed by mice model with transplanted tumor." (PMID 35517403, 2022). "Despite of these, to the best of our knowledge, the role in thyroid cancer played by CDCA8 has not been studied and remains largely unclear, which stimulates the performance of our study." (PMID 35517403, 2022). "Thyroid cancer cells lacking CDCA8 expression also had reduced tumorigenicity in vivo." (PMID 35517403, 2022). "Therefore, it was supposed in this study that CDCA8/CDK1 signaling may have substantial contribution in the development and progression of thyroid cancer." (PMID 35517403, 2022).
breast tumors (1 paper, 2024).
glaucoma (1 paper, 2022). Increased pressure in the eyeball due to obstruction of the outflow of aqueous humor. "For example, CDCA8, HLA-B, RHOC, PPM1J, RPL10A, and TEAD3 are associated with glaucoma (P < 1 × 10−6)." (PMID 36450729, 2022).
hepatitis B (1 paper, 2021). "Moreover, CDCA8 levels were found to be independent of age (p = 0.682), gender (p = 0.43), α‐fetoprotein (AFP) serum levels (p = 0.516), liver fibrosis (p = 0.29) and hepatitis B (p = 0.317)." (PMID 34741389, 2021).
kidney cancer (1 paper, 2023). Primary or metastatic malignant neoplasm involving the kidney. "The function of CDCA8 in kidney cancers should be further investigated." (PMID 37201027, 2023). "Here, we analyzed the SUMOylation-related gene expression status at the RNA level in kidney cancer tissues and built a risk model using three SUMOylation genes, CDH1, CDCA8, and PPARA, to indicate the outcomes based on differentially expressed SUMOylation genes." (PMID 37201027, 2023). "However, CDCA8 protein was downregulated in the CPTAC kidney cancer tissues and TMA tissues, which is contrary to the RNA level." (PMID 37201027, 2023). "At the RNA level, CDCA8 was overexpressed, while CDH1 and PPARA were downregulated in kidney cancer tissues, in TCGA-KIRC." (PMID 37201027, 2023). "However, CDCA8 protein was downregulated in CPTAC kidney cancer tissues assessed by proteome sequencing and in kidney cancer TMA tissues by the IHC method, which is contrary to the RNA level." (PMID 37201027, 2023). "In addition, three genes (CDCA8, CDH1, and PPARA) presented as independent factors of kidney cancer by multivariate cox regression." (PMID 37201027, 2023).
malignant glioma (1 paper, 2021). A grade III or grade IV glioma arising from the central nervous system. "Targeting CDCA8 or E2F1 exerted its antitumor effect in malignant glioma." (PMID 33542211, 2021).
metastatic disease (1 paper, 2025). "Among the nominated hub genes, CDCA8 and TROAP consistently emerged as markers of aggressive disease biology, demonstrating associations with subsequent metastasis in initially non-metastatic patients and with adverse survival among patients presenting with metastatic disease." (PMID 41008819, 2025). "CDCA8 and TROAP emerge as candidate prognostic biomarkers, linking postoperative metastatic progression in an initially M0 cohort with survival in metastatic disease." (PMID 41008819, 2025).
nasopharyngitis (1 paper, 2022). An inflammatory process that affects the nasopharynx. "IHC suggested that CDCA8 was highly expressed in NPC tissues and the expression of CDCA8 was very low in nasopharyngitis tissues." (PMID 35237510, 2022).
ovarian tumors (1 paper, 2024). "Except for ATAD2, expression of other genes (ASF1B, CCNE1, CDC20, CDCA8, RECQL4, RNASEH2A, and SMC4) was upregulated in ovarian tumors compared to non-cancerous tissue." (PMID 39199556, 2024).
renal carcinoma (1 paper, 2020). A carcinoma arising from the epithelium of the renal parenchyma or the renal pelvis. "With regard to renal cancer, CDCA8 has also certain prognostic value." (PMID 32104702, 2020).
uterine serous carcinoma (1 paper, 2020). "As to uterine serous carcinoma/uterine papillary serous carcinoma, the most common alterations were the high mRNA expression of all CDCA members, the amplification of CDCA5, CBX2 and CDCA8 and the missense mutation of CDCA2/7." (PMID 32913454, 2020).
tumor (68 papers, 2012 to 2026). "The result of model with 10 genes showed that 6 genes of MYCN, NDRG1, TXNRD1, SNAPC2, PHOSPHO2 and CDCA8 were more significantly associated with diagnosis of tumor according to the statistical filter of P < 0.05." (PMID 40465781, 2025). "Significantly, HIF1α proteins bind to CDCA8 promoter for transcriptional activation, forming a positive-feedback loop to sustain BCa tumor cells under oxygen-deficient environment." (PMID 37813876, 2023). "Herein, we examined the CDCA8 levels in tumor tissues, as well as its associated signaling pathways and correlation with immune infiltration." (PMID 36855818, 2023). "CDCA8 levels are elevated in a variety of tumor types where it has been implicated in the growth and tumor progression." (PMID 36248857, 2022). "Some essential genes (including CDCA8) were validated and found to be associated with tumor stage, metastasis, biochemical recurrence, and survival." (PMID 35449575, 2022). "In vivo recovery of E2F1 expression levels also rescued the tumour proliferation inhibition caused by CDCA8 knockdown." (PMID 34741389, 2021). "The neoantigen load had significant differences in CDCA1, CDCA2, and CDCA8, which indicated that these genes with low-methylation had powerful associations with weakening tumor immunogenicity." (PMID 33665158, 2020). "All these results reveal that the methylation states of CDCA1, CDCA2, and CDCA8 have strong associations in the tumor immunogenicity." (PMID 33665158, 2020). "Cell division cycle associated 8 is not only an oncogene to promote the occurrence and development of tumour but is also necessary for the proliferation and malignant development of cancer cells." (PMID 32377458, 2020). "Cell division cycle associated 8 (CDCA8), an important component of the vertebrate chromosomal passenger complex, is highly expressed in various tumours and promotes tumour development." (PMID 32377458, 2020). "Meanwhile, CDCA1–5 and CDCA8 demonstrated the weak correlations in the tumor purity, whereas the associations of CDCA6 and CDCA7 were weak and negative." (PMID 33665158, 2020). "Cell division cycle associated 8 (CDCA8) overexpression is detected in various malignant tumors and closely associated with tumor growth." (PMID 30142792, 2018). "CDCA8 expression was significantly associated with tumor progression (P = .001), T stage (P < .0001), N stage (P = .013), and grade (P < .0001)." (PMID 30142792, 2018). "The results showed that CDCA8 expression in tumor tissues was significantly associated with progression (P = .001), T stage (P < .0001), N stage (P = .013), and grade (P < .0001)." (PMID 30142792, 2018). "Taken together, the identified circRNAs and hub genes, as well as the CBT15_circR_28491-miR-139-3p-Kif18a/Cdca8/Nek2 axis, may be closely linked to the thrombotic risk associated with neoplasia and play essential roles in the progression of DVT." (PMID 40662137, 2025). "Cdca8, a critical regulator of mitosis, has been linked to increased growth of tumor cells." (PMID 40662137, 2025). "Despite multiple investigation identifying high levels of CDCA8 in HCC, as well as its association with tumor infiltration and metastasis, the correlation between CDCA8 levels and immune infiltration remains unclear." (PMID 36855818, 2023). "Furthermore, analysis of the demographic characteristics of patients with PDAC showed that CDCA8 expression was positively associated with tumor grade." (PMID 36358852, 2022). "However, CDCA8 overexpression offset the low proliferation rate of tumor cells caused by the knockdown of CD44." (PMID 36358852, 2022). "Moreover, overexpression of CDK1 could weaken the tumor suppressive effect caused by CDCA8 knockdown." (PMID 35517403, 2022). "Recently, it has been found that the upregulation of cell division cycle-associated 8 (CDCA8), a key protein for chromosomal segregation during mitosis, is associated with HCC metastasis by promoting DNA synthesis and thus tumor cell viability." (PMID 40149252, 2025).
tumor (continued). "Tumor tissues exhibited significant upregulation of CDCA8, AURKA, and PLK1, whereas NR3C2 was notably downregulated (p < 0.0001)." (PMID 41357242, 2025). "Across CDCA2, CDCA3, CDCA4, CDCA5, CDCA7, and CDCA8, we observed significantly lower promoter methylation levels in primary tumor samples compared to normal samples, suggesting hypomethylation of these genes in GBM tumors." (PMID 40114265, 2025). "Cell cycle regulating proteins such as CDCA4, CDCA8, and KIF2C have been linked to tumor growth and progression, affecting the proliferation, migration, invasion and metastasis of cancer cell lines." (PMID 38605349, 2024). "A high expression of CDCA8 has been associated with higher AFP, larger tumor size, pathological status, T stage, and poor prognosis in HCC." (PMID 38742112, 2024). "In the in vivo tumorigenic study, the MYBL2 knockdown group displayed a substantial decrease in tumor volume (P < 0.01) and exhibited decreased CDCA8 expression in tumors in comparison to the control group." (PMID 38961953, 2024). "The outcome revealed a notable decrease in tumor volume and CDCA8 protein expression in tumors in the MYBL2 knockdown group in comparison to the findings in the control group." (PMID 38961953, 2024). "Further, immunohistochemical staining for Ki-67 showed that CDCA8 promoted tumor growth in vivo, corroborating the proliferative effects of CDCA8 in HCC." (PMID 36639822, 2023). "Taken together, these results suggested that CDCA8 enhances the tumor growth and invasiveness of HCC cells via the MEK/ERK pathway." (PMID 36639822, 2023). "Previous studies have showed that CDCA8 overexpression drives malignant tumor behavior, growth, invasion, and metastasis in many types of cancers." (PMID 36639822, 2023). "We also observed similar results with the UMUC3 cells (a human transitional bladder carcinoma), affirming that CDCA8 plays a crucial role in tumor cells adaptation to the hypoxic environment." (PMID 37813876, 2023). "Elevated CDCA8 expression in HCC patients was markedly associated with T stage, pathological status (PS), tumor status (TS), histologic grade (HG), and AFP." (PMID 36855818, 2023). "Compared with the negative control (NC) group, the growth and the average weight of neoplasm were obviously restrained in CDCA8 silenced group." (PMID 37813876, 2023). "The results showed that CDCA8 levels were significantly positively associated with AFP levels (p = 0.003), tumor number (p = 0.007), and vascular invasion (p = 0.045)." (PMID 36639822, 2023). "An orthotopic tumor model and tail vein model were constructed to determine the effects of CDCA8 inhibition in vivo." (PMID 36639822, 2023). "In this study, we disclosed CDCA8 overexpression in BCa, and its expression positively correlated with the stage and grade of tumor." (PMID 37813876, 2023). "A previous study has clarified that KIF-18B was involved in the growth and progression of tumor cells by up-regulating transcription of CDCA8." (PMID 36358852, 2022). "The results indicated that CDCA8 expression was significantly positively correlated with tumor purity, infiltration levels of B cells, CD8+T cells, CD4+T cells, and macrophages in PCa." (PMID 35449575, 2022). "In our in vivo assays, we discovered that CDCA8 knockdown significantly inhibited the tumor volume, weight, and Ki-67 index of mouse models, indicating that CDCA8 plays a vital role in promoting the growth of PDAC." (PMID 36358852, 2022). "In this study, we also found that there was overexpression of CDCA8 in PDAC tumor tissues compared to that in adjacent tissues." (PMID 36358852, 2022). "High expression of CDCA8 correlates with tumor histological grade of PCa and predicts poor prognosis." (PMID 35449575, 2022). "According to the results, tumor cells overexpressing CDCA8 had the highest proliferation capacity, whereas tumor cells with knockdown of CD44 had the lowest proliferation capacity." (PMID 36358852, 2022).